COX6A1P2 (COX6A1 pseudogene 2)
Gene: Processed pseudogene on chromosome 6 (37,044,860 to 37,045,189, forward strand). Ensembl gene ENSG00000226976.
Diseases named in the same sentence as COX6A1P2 in open-access papers:
COX6A1P2 is named in the same sentence as 1 disease in open-access papers, as found by Europe PMC text mining. Sharing a sentence is not in itself a finding about the gene and the disease.
COX6A1P2 shares sentences with these, for which no sentence is quoted: Obesity (1 paper).